TRGV6 (T cell receptor gamma variable 6 (pseudogene))
Synonyms: V1S5P; TCRGV5P; formerly TCRGV6
Gene: T-cell receptor variable (V) pseudogene on chromosome 7 (38,340,700 to 38,340,998, reverse strand). Ensembl gene ENSG00000226212.
Diseases named in the same sentence as TRGV6 in open-access papers:
TRGV6 is named in the same sentence as 2 diseases in open-access papers, as found by Europe PMC text mining. Sharing a sentence is not in itself a finding about the gene and the disease. The quoted sentences say what the papers report.
tumor (2 papers, 2023 to 2024). "The expression of Trgv1, the gene encoding T cell receptor Vγ1 chain, but not Trgv4, Trgv5, Trgv6 or Trgv7 was also upregulated in tumours of Vil Apc Dock2 mice." (PMID 39242821, 2024).
TRGV6 also shares sentences with these, for which no sentence is quoted: prostate tumors (1 paper).